OR13C2 (olfactory receptor family 13 subfamily C member 2)
Description:
Odorant receptor.
Synonyms: OR37K
Tractability: Antibody: its Gene Ontology location is reachable by antibodies, with high confidence; UniProt places it where antibodies can reach, with medium confidence; UniProt predicts a signal peptide or a membrane-spanning region; the Human Protein Atlas places it where antibodies can reach.
Gene: Protein-coding gene on chromosome 9 (104,604,671 to 104,605,627, reverse strand). Ensembl gene ENSG00000276119.
Subcellular location: Cell membrane
Subcellular location (Human Protein Atlas): Plasma membrane; Nucleoplasm
Pathways (Reactome):
Sensory Perception: Expression and translocation of olfactory receptors
Gene Ontology:
Molecular function: olfactory receptor activity; G protein-coupled receptor activity
Biological process: detection of chemical stimulus involved in sensory perception of smell; G protein-coupled receptor signaling pathway
Cellular component: plasma membrane; membrane
Genetic constraint (gnomAD): Loss-of-function variants: 9 observed, 13.35 expected, observed/expected ratio (o/e) 0.67, 90% interval 0.41 to 1.18. The upper end of that interval is the gene's LOEUF score, 1.18, which puts it in group 5 of 6, group 1 being the genes least tolerant of losing a copy. Missense variants: 333 observed, 374.07 expected, observed/expected ratio (o/e) 0.89, 90% interval 0.81 to 0.98. Synonymous variants: 110 observed, 131.9 expected, observed/expected ratio (o/e) 0.83, 90% interval 0.71 to 0.98.
Homologues: Orthologues: chimpanzee OR13C2 (99% identical), dog OR13C2 (90% identical), dog OR13C2B (90% identical), rat Or13c9 (80% identical). Paralogues in human: OR13C5 (93% identical), OR13C9 (92% identical), OR13C4 (64% identical), OR13C3 (64% identical), OR2S2 (64% identical), OR13C8 (63% identical), OR13D1 (59% identical), OR2K2 (55% identical), OR13J1 (50% identical), OR2F1 (46% identical), OR2G3 (46% identical), OR5V1 (46% identical), and 80 more.